SLC16A12 (solute carrier family 16 member 12)
Description:
Functions as a transporter for creatine and as well for its precursor guanidinoacetate. Transport of creatine and GAA is independent of resting membrane potential and extracellular Na(+), Cl(-), or pH. Contributes to the process of creatine biosynthesis and distribution.
Synonyms: CRT2; MCT12; CJMG; CTRCT47
Tractability: Antibody: UniProt places it where antibodies can reach, with high confidence; its Gene Ontology location is reachable by antibodies, with high confidence; UniProt predicts a signal peptide or a membrane-spanning region.
Gene: Protein-coding gene on chromosome 10 (89,430,174 to 89,556,701, reverse strand). Ensembl gene ENSG00000152779.
Subcellular location: Cell membrane; Basolateral cell membrane
Gene Ontology:
Molecular function: creatine transmembrane transporter activity; protein binding; uniporter activity; transmembrane transporter activity
Biological process: creatine transmembrane transport; transport across blood-brain barrier; creatinine metabolic process; transmembrane transport
Cellular component: plasma membrane; basolateral plasma membrane
Genetic constraint (gnomAD): Loss-of-function variants: 19 observed, 44.78 expected, observed/expected ratio (o/e) 0.42, 90% interval 0.29 to 0.62. The upper end of that interval is the gene's LOEUF score, 0.62, which puts it in group 2 of 6, group 1 being the genes least tolerant of losing a copy. Missense variants: 528 observed, 641.75 expected, observed/expected ratio (o/e) 0.82, 90% interval 0.76 to 0.88. Synonymous variants: 219 observed, 239.07 expected, observed/expected ratio (o/e) 0.92, 90% interval 0.82 to 1.02.
Homologues: Orthologues: chimpanzee SLC16A12 (99% identical), macaque SLC16A12 (99% identical), dog SLC16A12 (87% identical), pig SLC16A12 (86% identical), rabbit SLC16A12 (85% identical), guinea pig SLC16A12 (83% identical), mouse Slc16a12 (82% identical), rat Slc16a12 (81% identical), tropical clawed frog slc16a12 (66% identical), zebrafish slc16a12b (59% identical), zebrafish slc16a12a (55% identical), Drosophila melanogaster Mct1 (28% identical), and 12 more. Paralogues in human: SLC16A8 (31% identical), SLC16A3 (30% identical), SLC16A7 (27% identical), SLC16A1 (26% identical), SLC16A11 (26% identical), SLC16A13 (26% identical), SLC16A14 (25% identical), SLC16A5 (25% identical), SLC16A4 (24% identical), SLC16A6 (24% identical), SLC16A9 (24% identical), SLC16A10 (21% identical), and 1 more.
Diseases named in the same sentence as SLC16A12 in open-access papers:
SLC16A12 is named in the same sentence as 26 diseases in open-access papers, as found by Europe PMC text mining. Sharing a sentence is not in itself a finding about the gene and the disease. The quoted sentences say what the papers report.
prostate carcinoma (4 papers, 2008 to 2021). A carcinoma that arises from epithelial cells of the prostate gland. "Since most PUVs localize directly in the prostatic urethra, the association of SLC16A12 with prostate cancer seems interesting." (PMID 34573432, 2021). "Nevertheless SLC16A12 has been shown to be expressed in the early embryonic mouse kidney at E17.5 and has been discussed as a potential biomarker for human prostate cancer." (PMID 34573432, 2021). "Moreover, microdeletions of chromosomal band 10q23.31 encompassing SLC16A12 and PANK1 have directly been associated with prostate cancer." (PMID 34573432, 2021). "Among epigenetic biomarkers, most reports indicate GSTP1 hypermethylation as the diagnostic marker for prostate cancer; however, NKX2-5, CLSTN1, SPOCK2, SLC16A12, DPYS, and NSE1 also have been reported to be regulated by methylation mechanisms in prostate cancer." (PMID 24213111, 2011). "Interestingly, SLC16A12 has also been discussed as a potential biomarker for human prostate cancer." (PMID 34573432, 2021). "Based on methylation in primary tumors compared to normal adjacent tissues, NKX2-5, CLSTN1, SPOCK2, SLC16A12, DPYS and NSE1 are candidate biomarkers for prostate cancer (methylation range 50%–85%)." (PMID 18446232, 2008). "Compared to adjacent normal prostate, all 8 genes had significantly higher methylation in prostate cancer by t-test analysis (P<0.001 for NKX2-5; P<0.001 for SPOCK2; P = 0.004 for GALR2; P<0.001 for CLSTN1; P<0.001 for NSE1; P<0.001 for DPYS; P = 0.019 for FOXN4; P<0.001 for SLC16A12)." (PMID 18446232, 2008).
Microcornea (3 papers, 2012 to 2019). A congenital abnormality of the cornea in which the cornea and the anterior segment of the eye are smaller than normal. "While specific corneal functions of many of these solute carrier family members are not known, it is noteworthy that mutations in SLC4A11 and SLC16A12 are associated with congenital hereditary endothelial dystrophy (CHED) and microcornea, respectively." (PMID 23024760, 2012).
Renal glucosuria (3 papers, 2011 to 2024). "Other examples where early onset cataract is the major manifestation of an underlying systemic disorder include renal glucosuria due to solute carrier family 16, member 12 (monocarboxylic acid transporter 12; SLC16A12) mutations, and lactose intolerance due to galactokinase 1 (GALK1) mutations." (PMID 21541272, 2011). "A nonsense mutation in the gene for monocarboxylate transporter 12 or creatine transporter 2 (SLC16A12) on chromosome 10q, was first shown to underlie autosomal dominant juvenile cataract with or without microcornea and renal glucosuria." (PMID 38927721, 2024).
Age-related cataract (2 papers, 2022). A type of cataract (opacification of the lens) that forms during the course of aging. "Except for these genes involved in inherited diseases, mutations of SLC16A12 may function in age-related cataracts through influencing lens homeostasis." (PMID 35456484, 2022). "At least 8 genes are known to be directly associated with age-related cataracts, including EPHA2, GJA8, GALT, SLC16A12, HSF4, GALK1, FTL, and CRYAA." (PMID 36107580, 2022).
breast carcinoma (2 papers, 2008 to 2019). "Compared to adjacent normal breast, all 6 genes except NKX2-5 showed higher methylation in breast cancer by t-test analysis (P<0.001 for DPYS and EGFR5 P = 0.01 for SLC16A12; P = 0.002 for TOX; P = 0.003 for GALR2)." (PMID 18446232, 2008). "Finally, SLC16A12, GALR2, TOX, SPOCK2, EGFR5 and DPYS are candidate biomarkers for breast cancer (methylation range 33%–79%) with the combination of EGFR5 or TOX hypermethylation showing a sensitivity of 92% and specificity of 92%." (PMID 18446232, 2008).
clear cell renal cell carcinoma (2 papers, 2019 to 2021). "However, the clinical values of SLC16A12 in clear cell renal cell carcinoma (ccRCC) have not been explored." (PMID 31348313, 2019).
colon cancer (2 papers, 2008 to 2019). "In a panel of 20 colon cancer cases, all these genes except IRX5, TFAP2E and TFAP2C showed significantly higher methylation in cancer by t-test analysis (P<0.001 for NKX2-5, DPYS SPOCK2, GALR2 and SLC16A12; P = 0.008 for FOXN4)." (PMID 18446232, 2008). "Similarly NKX2-5, SPOCK2, SLC16A12, DPYS and GALR2 are candidate biomarkers for colon cancer (methylation range 60%–95%) and GALR2 hypermethylation showed a sensitivity of 85% and specificity of 95%." (PMID 18446232, 2008).
kidney cancer (2 papers, 2018 to 2022). Primary or metastatic malignant neoplasm involving the kidney. "In our study, we found MAP7, SLC16A12, and SLC27A2 in kidney cancer cells when compared with normal kidney cells, which agreed with the results of the TCGA-KIRC." (PMID 36620592, 2022). "The results revealed that the basal expression profiles of MAP7, SLC16A12, and SLC3A1 were high in kidney cancer cells." (PMID 36620592, 2022).
cataract (1 paper, 2010). Partial or complete opacity of the crystalline lens of one or both eyes that decreases visual acuity and eventually results in blindness. "Finally, variations in at least eight genes underlying genetic forms of cataract (EPHA2, GJA8, GALT, SLC16A12, HSF4, GALK1, FTL, and CRYAA), and at least 10 other diverse genes have been associated to varying degrees with age-related cataract." (PMID 21042563, 2010).
chronic renal failure (1 paper, 2024). "SLC16A12 is an identified creatine transporter, the lack of SLC16A12 usually leads to the low levels of creatine in chronic renal failure, and the comparatively lower expression of SLC16A12 in tumors often correlates with the worst prognosis." (PMID 39247556, 2024).
lymph node metastasis (1 paper, 2025). "Additionally, we also elucidated the correlation between SLC16A12&SMIM24 and clinical stage of ccRCC, results showed that in the patients with advanced stage including distant metastasis or lymph node metastasis, both two genes demonstrated lower expression." (PMID 40099255, 2025).
pancreatic cancer (1 paper, 2020). "Moreover, SLC16A10 and SLC16A12 were expressed at lower levels in pancreatic cancer." (PMID 32355273, 2020).
tuberculosis (1 paper, 2013). A chronic, recurrent infection caused by the bacterium Mycobacterium tuberculosis. "The SLC16A12 gene was also detected, a member of a gene family containing genes recently shown to be associated with tuberculosis susceptibility in cattle." (PMID 23565803, 2013).
type 2 diabetes (1 paper, 2021). "Existing studies have confirmed that MCT11(SLC16A11) and MCT13(SLC16A13) are related to type 2 diabetes, and MCT12(SLC16A12) is involved in the development of juvenile cataracts." (PMID 34424811, 2021).
cancer (7 papers, 2008 to 2025). A tumor composed of atypical neoplastic, often pleomorphic cells that invade other tissues. "Innovatively, we developed a prognostic risk model using LASSO and Cox regression on three hub genes (WDR72, ANLN, SLC16A12), integrating multi-omics data for immune microenvironment, tumor mutation burden (TMB), cancer stem cell (CSC) index, and drug sensitivity assessment." (PMID 41332473, 2025). "These genes are PLAUR, UCN, PABPC1L, SLC16A12, NFE2L3, and KCNAB1, and some of them have been previously reported in multiple types of cancer." (PMID 35211477, 2021). "We have selected five PCGIs (IGF2, SLC16A12, SOX11, P2RX7 and MYOD1) from cancer and inflammation/age related panels." (PMID 27259265, 2016). "Finally, RT-PCR showed that MAP7, SLC16A12, and SLC27A2 decreased, while SLC3A1 increased, in cancer cells." (PMID 36620592, 2022).
tumor (5 papers, 2019 to 2025). "RT-qPCR validated differential expression of WDR72, ANLN, and SLC16A12 in normal renal versus ccRCC tumor tissues, supporting their potential as diagnostic and therapeutic biomarkers." (PMID 41332473, 2025). "In other words, the expression of SLC16A12 mRNA was negatively associated with malignant tendency of the tumor." (PMID 31348313, 2019). "RT‒qPCR was then conducted to compare mRNA expression levels of WDR72, ANLN, and SLC16A12 in adjacent normal and ccRCC tumor tissues." (PMID 41332473, 2025). "Compared with paracancerous tissue, SLC16A12 was significantly downregulated in the tumor tissues both in mRNA and protein level." (PMID 31348313, 2019). "The expression of SLC16A12 mRNA in normal and tumor tissues were compared in TCGA-KIRC database, compared to the normal kidney tissues, SLC16A12 mRNA expression was significantly downregulated in tumor tissues (P < .001)." (PMID 31348313, 2019). "After the analysis of 75 ccRCC cases, we demonstrated that the sections lowly and moderately expressed SLC16A12 accounted for a majority of tumor tissues." (PMID 31348313, 2019). "A recent study showed that SLC16A12 can be a prognostic factor for patients in KIRC, indicating that SLC16A12 might be a critical tumor suppressor." (PMID 33209196, 2020). "Overall, these data suggest that SLC16A12 functions as a potential tumor suppressor in ccRCC, which could be a therapeutic target in limiting the progression of ccRCC." (PMID 31348313, 2019). "Besides, the IRS of SLC16A12 in the tumor tissues was notably lower than paired normal tissues (P < .001)." (PMID 31348313, 2019). "Moreover, the protein abundance of SLC16A12 in normal and tumor tissues was also quantified by IHC for validation." (PMID 31348313, 2019). "Given to all the findings, we suggest that SLC16A12 may play an important role of tumor suppressor in the carcinogenesis of ccRCC, and that this may be a potential target to limit the progression of ccRCC." (PMID 31348313, 2019). "The results revealed ANLN upregulation and SLC16A12 and WDR72 downregulation in ccRCC tumor tissues compared to adjacent normal tissues." (PMID 41332473, 2025). "PLAUR, PABPC1L, SLC16A12, NFE2L3, and KCNAB1 presented significantly different expression levels between tumor tissues and normal tissues." (PMID 35211477, 2021).
infection (1 paper, 2023). The state of being infected such as from the introduction of a foreign agent such as serum, vaccine, antigenic substance or organism. "Many solute carrier (SLC) family genes were also activated at 24 or 48 h after infection, including SLC16A12, SLC2A3, SLC16A6, and SLC32A1." (PMID 37211158, 2023).
SLC16A12 also shares sentences with these, for which no sentence is quoted: gastric cancer (2 papers); bacterial infections (1); colorectal cancer (1); creatine transporter deficiency (1); epilepsy (1); gastritis (1); inherited diseases (1); Peters plus syndrome (1); renal carcinoma (1).